CDK1 (cyclin dependent kinase 1)
Diseases named in the same sentence as CDK1 in open-access papers (continued):
Sharing a sentence is not in itself a finding about the gene and the disease.
tumor (continued). "Selective targeting of CDK1 might constitute a novel strategy for tumor treatment in certain contexts." (PMID 30931929, 2019). "Cdk1 and 2 were reduced by temsirolimus in the parental but enhanced in the resistant tumor cells." (PMID 31167517, 2019). "According to the concept of SL, using Alvocidib to target CDK1 may selectively kill specific gene mutant tumor cells." (PMID 29855504, 2018). "Reconstitution of p21 expression in brachyury-high tumor cells was shown to increase the stability of the CDK1 protein while markedly increasing the lysis mediated by antigen-specific CD8+ T cells, NK and LAK cells, TNF-related apoptosis-inducing ligand (TRAIL) and chemotherapy." (PMID 29774202, 2018). "miR-490-3p acts as a tumor suppressor by targeting CDK1 in EOC, and DLEU1 may promote tumorigenesis by inhibiting miR-490-3p function." (PMID 30069008, 2018). "In the present study, the CDK1/2/9 inhibitor AZD5438 exerted significant tumor inhibition in two PDX models with high copy number of CCNE1, and we also found that AZD5438 exerted antitumor activity by inhibiting the expression of CDK2, CCNE1, and phosphorylated retinoblastoma (pRb)." (PMID 29433585, 2018). "This defect was due to the loss of the protein kinase CDK1 in brachyury-high tumor cells, although the mechanism of CDK1 protein destabilization was not understood at the time." (PMID 29774202, 2018). "TTK, AURKA, BUB1, CDK1 and NEK2 were fundamental kinases with high node degree, which may be required for maintaining the molecular signals underlying tumor progression." (PMID 30598639, 2018). "Despite the critical role of CDK1 in mammalian cell cycle progression and its importance in tumor formation, the mechanism by which CDK1 is degraded via the lysosomal pathway is unknown." (PMID 28855742, 2017). "Cyclin-dependent kinase 1 (CDK1), a key player which promotes G2-M transition, regulates G1 progress and G1-S transition through associating with multiple interphase cyclins, has been reported to be upregulated in CRC circulating tumor cells." (PMID 29069733, 2017). "In addition, cytoplasmic Cdk1 expression increased in accordance with progression of tumor grade (p < 0.001)." (PMID 27385216, 2016). "Therefore, it is evident that increased activation of the cyclin B/cdk1 complex leads to centrosome amplification, aneuploidy and tumor formation." (PMID 27253419, 2016). "Moreover, CDK2 has been reported to be essential for cell proliferation in several human tumours and emerging data have suggested that CDK1 or CDK2 can be considered as the most appropriate CDKs to target in combination with DNA-damaging agents." (PMID 27898692, 2016). "Our work demonstrates that rather than inhibiting cdk1 activity, a novel way of inhibiting tumor growth might be the premature activation of cdk1 in interphase cells." (PMID 27253419, 2016). "In combination with the increased ROS levels generated by hyperthermia, this might be the reason for the more significant decrease of Cyclin B1 and CDK1 in tumours co-treated with hyperthermia and 17-DMAG." (PMID 27909289, 2016). "Both these series of compounds showed antiproliferative activity against a wide range of human tumor cell lines in the micromolar-submicromolar range and were able to inhibit the activity of the cyclin-dependent kinase 1 (CDK1) with GI50 values lower than 1 μM." (PMID 25603343, 2015). "Cdk1 is located at the end of the G2/M signaling pathway, and is therefore key in the G2/M arrest and cell apoptosis induced by chemotherapy and radiotherapy in tumor cells." (PMID 25663895, 2015). "In the cell cycle, Cdk1 is a master modulator of initiation and transition through mitosis, with high active Cdk1 expression levels able to promote G2/M transition and accelerate tumor cell growth." (PMID 25663895, 2015). "In addition, CDK1 was reported to be a useful biomarker for HCC to distinguish from non-tumor liver." (PMID 26536659, 2015).
tumor (continued). "Our results confirm an essential role for the cdk1/CCNB1 complex in tumor cell survival." (PMID 26029996, 2015). "To summarize, sorafenib added to sunitinib-sensitive tumour cells reduced cdk1 and cdk2 and enhanced p19 and p27 (with slight differences among the cell lines), whereas sorafenib added to sunitinib-resistant cells time-dependently elevated cdk1 and cdk2 and down-regulated p19 and p27." (PMID 25444514, 2015). "Also, inhibition of cyclin B1/Cdk1 activity has been shown to increase apoptosis in human tumour cells 36,37." (PMID 24266894, 2014). "PPP treatment was associated with CDK1 activation in all tumor cell lines and in the A549 xenografts, whereas no CDK1 activation was detected in normal human hepatocytes or in normal lung tissue." (PMID 25268741, 2014). "Are such effects evident in different cellular responses involving VEGFR2 and/or CDK1 that could contribute to growth of a neovascularized tumor?" (PMID 25393739, 2014). "Finally, in different tumor types from patient samples, we showed an inverse correlation between CDK1 accumulation and βTrCP levels." (PMID 25149538, 2014). "Notably, this applies to a compact module of cell cycle regulators, namely survivin, cyclin B1, Cdk1, Plk1, and Bub1, whose expression increased about 2-fold in tumor versus transgenic cells according to measured fold changes." (PMID 21464922, 2011). "Importantly, our pharmacodynamic analysis showed that these tumor responses correlated with the degree and duration of STAT5 and Cdk1 protein loss induced by the varying dosing regimens." (PMID 21533169, 2011). "The downregulated CDK1 in Her2BC suggests a dysregulated cell cycle, where the bioactive compounds in OT could modulate through the disruption of the G2/M transition, leading to cell cycle arrest and thereby suppressing tumor cell proliferation." (PMID 40427676, 2025). "Moreover, API specifically inhibits CDK1/2 activity, resulting in G2/M phase arrest in tumor cells." (PMID 41226659, 2025). "Moreover, ongoing studies target the identified genes (ENO1, STMN1, PKM, CDK1), with therapies like enolase 1 depletion demonstrating efficacy across various tumor types by inhibiting glycolysis, growth, proliferation, migration, metastasis, and sensitizing tumors to chemotherapy and radiotherapy." (PMID 38840205, 2024). "In addition, CDK1 might also play a role in regulating processes in the tumor microenvironment (TME), such as NK/T-cell activation and CD4-positive alpha beta T-cell proliferation." (PMID 36950551, 2023). "Regarding DNA methylation, we discovered that there was no apparent difference in the methylation level of CDK1 between tumor and normal samples, indicating that the promoter methylation of CDK1 may not cause changes in the mRNA level." (PMID 36950551, 2023). "CDK1 stabilization could further promote tumor deterioration and poor prognosis." (PMID 37667382, 2023). "In addition, CDK1, CDC20, CCNA2, CCNB1 and CCNB2 expressions may be involved in the regulation of monocytes and tumor-associated macrophages (TAMs) in HCC, respectively." (PMID 36605491, 2023). "However, there have been few studies on the relationship between CDK1 and tumor metastasis or EMT." (PMID 36184616, 2022). "Therefore, we analyzed the correlation between tumor mutation burden and the expression of targets, and the results showed that the expression of AURKA, CCNA2, CCNE1, CDK1, CHEK1, and PLK1 were significantly positively correlated with the tumor mutation burden." (PMID 36483630, 2022). "Therefore, our study demonstrated the tumor-promoting role of NLE1 in NSCLC which may be mediated by CDK1." (PMID 36818671, 2022). "The inclusion of CDK1 in tumor marker testing is of great significance, as well as the development of new anti-CDK1 drugs targeting CDK1, anti-CDK1 combined with immunotherapy or combined with chemotherapy, making it possible to extend the median survival time of tumor patients." (PMID 36090896, 2022).
tumor (continued). "PIKMT1 might be expected to act as a tumor suppressor by preventing Cdk1 activation." (PMID 35884597, 2022). "Our results showed that protein phosphorylation levels in tumor tissues were significantly higher than those in normal tissues; dysregulation of CDK1 protein phosphorylation may alter the activity of oncogenic-related signaling pathways and contribute to the formation of associated tumor phenotypes." (PMID 36090896, 2022). "Therefore, our next research focus is to determine that HNTX-III may be a novel microtubule stabilizer that inhibits tumor metastasis and induces apoptosis by significantly enhancing CDK1 activity, and to try to explore its mechanisms." (PMID 34437425, 2021). "Results showed that um-PEA inhibited tumor cell proliferation via peroxisome proliferator-activated receptor α and G protein-coupled receptor 55, induced cell cycle arrest in the G2/M phase, possibly through cyclin B1/CDK1 upregulation, and induced DNA fragmentation." (PMID 33923494, 2021). "CDK1 may play a role in early diagnosis, tumour stage, and poor outcomes of HBV-HCC." (PMID 34603487, 2021). "Furthermore, siRNA-based screening might help to identify CDK1 as a target in tumour tissue, but this technique needs to be optimised further before being used to select PDAC patients likely to respond to CDK inhibition." (PMID 34503199, 2021). "Therefore, its down-regulation—consequently reducing the activity of Cdk1/Cyclin B1—could block the aggressive proliferation of tumor cells." (PMID 34944868, 2021). "Thus, the increased Cdk1 and Plk1 expression in MmuPV1-induced tumor tissues may promote the expression and phosphorylation of CtIP." (PMID 34343212, 2021). "Therefore CDK1 inhibition has been proposed to be an attractive anti-tumor strategy." (PMID 33805800, 2021). "Therefore, it may be of guiding significance for tumor therapy to uncover the multifaceted function and mechanism of CDK1 in cells." (PMID 34499615, 2021). "Since previous experiments found that high iodine can induce the proliferation of BCPAP and 8305C cells by activating AKT/Wee1/CDK1 axis, we discussed whether AKT/Wee1/CDK1 was involved in the tumor growth of xenograft tumor models of PTC and ATC cells induced by high iodine." (PMID 33796458, 2021). "CDK1 expression is positively correlated with tumor stemness indices, and growing evidence suggests that the key biological processes of tumors, such as invasion, metastasis, and therapeutic resistance to chemotherapy and radiotherapy, are largely dependent on tumor stem cells." (PMID 34262594, 2021). "In addition to CDK4 and CDK5, cyclin-B/CDK1 may play a role in tumor cell spreading, motility, and invasion." (PMID 33723248, 2021). "Thus, BITC reduced cyclin B1 and Cdk1 levels, inducing apoptosis to suppress tumor growth." (PMID 33263014, 2020). "Additionally, higher mRNA levels of CDK1 and CEP55 were associated with tumor grade." (PMID 32587798, 2020). "Specifically, whereas subtype-1 tumours show upregulation of mTOR signalling associated kinases (among others, MTOR-pS2448, GSKB-pS21-S9, and PDK-pS241), subtype-2 tumours display upregulation of cell cycle associated kinases (among others, CDK1-pY15, p27-pT158, and p27-pT198)." (PMID 31988390, 2020). "Moreover, high levels of CDK1 expression is predictive of tumor recurrence." (PMID 32018226, 2020). "Regarding CCNB2 and CDK1, a recent study with primary HCC tissue samples showed that the downregulation of CCNB2 and CDK1 led to the inhibition of cell proliferation and cell cycle shutdown in the G2/M phase, indicating that the overexpression of CCNB2/CDK1 may promote tumour cell proliferation." (PMID 31754223, 2019). "Therefore, up-regulation of cdk1/cyclin B and cdk2/cyclin A might be partly responsible for tumor progression after long-term temsirolimus exposure." (PMID 31167517, 2019).
tumor (continued). "GO and KEGG pathway analysis, as well as experimental observation showed that CBX3 may be associated with cell cycle transition of PAAD cells, and cyclin-dependent kinase 1 (CDK1) and proliferating cell nuclear antigen (PCNA) may mediate the tumor-promoting action of CBX3." (PMID 29903985, 2018). "We observed that CDK1 may mediate the tumor-promoting role of CBX3 in PAAD." (PMID 29903985, 2018). "Interestingly, only cyclin-dependent kinase 1 (CDK1) showed overexpression in the tumor." (PMID 30283446, 2018). "The expression of Ccna2, Ccnb2, and Cdk1 were low, which could reduce G1/S-phase arrest and the transition from G2 to M phase, furthermore enhanced the ability of anti-apoptosis of tumor stem cells." (PMID 28163656, 2017). "This established that the KRAS/CDK1 synthetic lethality applies in tumour cells with either amino acid position 12 (p.G12V, pG12D, p.G12S) or amino acid position 13 (p.G13D) KRAS mutations and can also be replicated in vivo in a xenograft model using a small molecule CDK1 inhibitor." (PMID 26881434, 2016). "However, high level of CDK1 activation might sensitize tumor cells to stresses either from nutrient depletion or chemotherapy treatment." (PMID 21887332, 2011). "The free radical scavenging potential of Salvia coccinea and apigenin is responsible for reduced oxidative stress and tumor cell metastasis modulated through PARP-cleavage, caspase-3, ERK, CDK-1, JAK2/STAT3, Bax/Bcl-2, AMPK, and Wnt/β-catenin pathways." (PMID 41640995, 2026). "Pharmacological inhibition of CDK1 using RO-3306 suppresses KAT8 phosphorylation and H4K16 acetylation, leading to significant tumor growth inhibition." (PMID 42193906, 2026). "Therapies targeting G2/M checkpoint proteins (e.g., CDK1, Wee1, CHK1/CHK2) are being actively explored to control tumor growth and improve treatment outcomes." (PMID 40894036, 2025). "In vitro and in vivo models show that NiNPs activate the CDK1/STAT3/FASN axis to disrupt FAM homeostasis, conferring metabolic advantages for tumor cell proliferation and migration." (PMID 41226659, 2025). "A study based on microarray data identified five genes (CDK1, CDC20, CCNB1, CENPF, and MAD2L1) related to the tumor stage, early diagnosis, and poor outcomes." (PMID 40282296, 2025). "In conclusion, CACYBP appears to function as a tumor promoter in LUAD, at least in part through CDK1-mediated activation of the PI3K/AKT pathway." (PMID 40167359, 2025). "Dinaciclib, a potent CDK1, -2, -5 and -9 inhibitor, induces a type I IFN gene signature in various tumor cells." (PMID 40175357, 2025). "In vivo experiments supported these findings, as curcumin treatment significantly reduced tumor growth in mice, accompanied by increased miR-134-5p expression and reduced CDCA3 and CDK1 levels." (PMID 40969596, 2025). "Immunohistochemical analysis revealed elevated H scores for CDK1, STAT1, COL1A2, and COL1A1 in tumor tissues." (PMID 39911265, 2025). "According to the UALCAN database, the expression levels of PVT1, hsa-miR-143–3p, CDK1, FOXC1, YY1, and GATA2 show statistically significant differences between primary tumor samples and normal samples in the TCGA-LUAD dataset." (PMID 41080754, 2025). "Key findings indicate that Episesamin targets and downregulates critical cell cycle genes CDK1, CDC25A, and PLK1, potentially inducing cell cycle arrest and inhibiting tumour growth." (PMID 40081286, 2025). "The discovery that CDK1, TOP2A, AURKA, TPX2, BUB1B, and CENPF are key cell-cycle regulators in NSCLC emphasizes the ongoing contribution of mitotic dysregulation to tumor growth." (PMID 41080754, 2025).
tumor (continued). "To investigate the anti-tumor mechanisms of AZD1775, we examined the protein expression levels of p-WEE1 (Ser642), p-CDK1 (Tyr15), and p-γH2AX (Ser139) in PDX tumor lysates using Western blot." (PMID 40551232, 2025). "The analysis revealed that the five key genes, including BUB1, BUB1B, CDK1, UBE2C, and CCNA2, exhibited higher expression in LUAD tumor tissues compared to normal tissues in all cases." (PMID 41181148, 2025). "However, in the presence of circ‐Ccnb1, the interaction between Ccnb1 and Cdk1 was dissociated, accompanied by the formation of a large complex containing circ‐Ccnb1, Ccnb1 and Cdk1, resulting in inhibited Ccnb1 function as well as suppression of tumour growth." (PMID 41284375, 2025). "In vivo experiments confirmed that AS/BJO-NEs significantly inhibited tumor growth and reduced the expression of CDK1 and MTFR2 in tumor tissues." (PMID 40748969, 2025). "Third, CDK1-mediated phosphorylation was essential for USP33 binding to SIN1 and promoting tumor progression." (PMID 40695806, 2025). "Patients whose tumour had high expression of MAP1LC3A, SNCA, and MAPT and low expression of CDK1, AP1S1, CASP3, TMPRSS6, and GSK3B inferred better overall survival than all other patients." (PMID 38642129, 2024). "The expression of four genes (TOP2A, CDK1, CCNA2, and CCNB2) with high scores in module 1 were more in tumor samples and have been identified by GEPIA analysis." (PMID 38895552, 2024). "Compared to the control group after 48 h of treatment with TGT, the expression of genes JUN, TYMS, HSP90AA1, HDAC1, CDK1, and ESR1 was downregulated, which showed inhibitory effect on tumor cell proliferation." (PMID 38297292, 2024). "According to human data derived from the TCGA and GTEx databases, decreased expressions of miR-4516 and increased expressions of Wnt 8B, DVL3, FOSL1, CCNA1, CCNB1, CDK1, and CDK2 in tumor tissue contributed to the progression of LUAD." (PMID 38930863, 2024). "IHC experiments displayed that the positive expressions of Ki67(a well-known marker of cell proliferation), OTUD4, CDK1, FGFR1 and p-BRAF were obviously decreased in tumor xenografts with OTUD4 knockdown." (PMID 38429268, 2024). "A study emphasizes the importance of cell cycle regulators, such as CDK1 and cyclins, in NSCLC, indicating that targeting these regulators can inhibit tumor growth and induce apoptosis in NSCLC cells." (PMID 39457373, 2024). "On the other hand, it can reduce the expression of cell cycle proteins such as Cyclins B1, Cyclins D1, CDK1, CDK2, and CDK4, preventing the transition of tumor cells from the G2 phase to the M phase and inhibiting cell proliferation." (PMID 39274982, 2024). "The significant enrichment of the “Cell cycle” pathway across these modules highlights the importance of CDK1 and CDC20 in NSCLC, as their dysregulation contributes to tumor aggressiveness and resistance to treatment." (PMID 39457373, 2024). "Through a correlation analysis of GBM tumor samples, along with cellular assays of SRSF9 knockdown and overexpression, we revealed that SRSF9 positively regulates the expression of CDK1, a cell cycle controller." (PMID 38842611, 2024). "Hub genes, including PLK1, CDK1, and EGFR, emerged as critical regulators of tumor proliferation and immune responses." (PMID 39457373, 2024). "Key hub genes, such as PLK1, CDK1, and EGFR, emerge as crucial regulators of tumor proliferation, signal transduction, and immune response." (PMID 39457373, 2024). "We have presented data to show that for the alterations in cell growth and apoptosis observed in either the KO cells or the ccRCC tumours, the key HNRNPD downstream effector is CDK1." (PMID 39180763, 2024).